ERBB2 (erb-b2 receptor tyrosine kinase 2)
Diseases named in the same sentence as ERBB2 in open-access papers (continued):
Sharing a sentence is not in itself a finding about the gene and the disease.
prostate carcinoma (continued). "17-AAG was shown to radiosensitize prostate cancer and glioma cell lines exhibiting the now familiar molecular signature of depletion of radioresistance markers and HSP90 client proteins AKT, ErbB2 and cRAF." (PMID 22523597, 2012). "However, clinical trials of ErbB2-targeted therapies have not shown efficacy in prostate cancer patients prior to androgen deprivation therapy or in CRPC." (PMID 35645241, 2022). "However, by using logistic regression strategy, we found and validated that several VUS-containing genes (COL1A1, CSF3R, ERBB2, ITGB8, TSC1 and TSC2) in the PI3K-Akt signaling pathway can improve the predicting of metastasis in prostate cancer patients in Hong Kong and Shanghai cohorts." (PMID 36095024, 2022). "Our data suggest that ERBB2 collaborates with androgen signaling to promote prostate cancer metastasis, and that although RAS is one of the critical downstream effectors of ERBB2, it does not phenocopy ERBB2 for its impact on the metastatic potentials of prostate cancer cell lines." (PMID 24937171, 2014). "We have shown that overexpression of the constitutively activated form of ERBB2 (NeuT) increases the metastatic potential of the two androgen-insensitive human prostate cancer cell lines, DU145 and PC3, but not that of the two androgen-sensitive prostate cancer cell lines, LnCaP and Myc-CaP." (PMID 24937171, 2014). "However, overexpression of ERBB2 did not affect the growth rate of the murine prostate cancer cell line, Myc-CaP." (PMID 24937171, 2014). "However, we found that this mechanism is unlikely to have a role in PC3 prostate cancer cells, as they express low levels of ErbB2 and the treatment with the kinase inhibitor lapatinib didn’t seem to interfere with Sema3E/PlexinD1-mediated effects (M.R., unpublished results)." (PMID 27749937, 2016). "However, subcutaneous administration of the same single-cell clone (N35) and the other ERBB2-overexpressing single-cell clone into athymic nude mice did not induce metastasis, suggesting that the ability of ERBB2 to induce prostate cancer metastasis depends on an appropriate host microenvironment." (PMID 24937171, 2014). "Collectively, these data demonstrate that KLF5 overexpression regulates ERBB2 expression in AR-positive prostate cancer cells and more broadly regulates ERBB2-related genes LGALS7 and FAM129B in prostate cancer cells regardless of cellular AR status." (PMID 34737261, 2021). "In the present study, we used three complementary approaches to assess the effect of ERBB2- and RAS-overexpression on the metastatic potentials of three metastatic human prostate cancer cell lines and one non-metastatic mouse prostate cancer cell line that have different androgen-sensitivities." (PMID 24937171, 2014). "LNCaP prostate carcinoma cells, three pancreatic cells (Miapaca-2, Capan-2 and CF-PAC-1) and three colon cancer cells (HCT116, COLO 205 and COLO 320) showed a significant increase in erbB-2 mRNA levels without gene amplification." (PMID 12942124, 2003). "We showed that while overexpression of ERBB2 increased the metastatic potential of the androgen-insensitive prostate cancer cells (i.e. PC3 and DU145), it did not affect metastatic potentials of the androgen-sensitive prostate cancer cells (i.e. LnCaP and Myc-CaP)." (PMID 24937171, 2014).
glioblastoma (353 papers, 2003 to 2026). The most malignant astrocytic tumor (WHO grade IV). "ERBB2 has been implied as an appropriate target for CAR T cells in glioblastoma, its expression is often associated with high-grade gliomas." (PMID 37221474, 2023). "For instance, Val644 to Glu mutation within the TM domain of ErbB2/Neu is associated with an uncontrolled activation of this RTK leading to glioblastomas in rats." (PMID 32351895, 2020). "High serum EGFR and ErbB2 levels were associated with risk of developing glioblastoma (P = 0.008; OR = 1.58, 95 % CI = 1.13–2.22 and P = 0.017, OR = 1.63, 95 % CI = 1.09–2.44, respectively)." (PMID 26906551, 2016). "By dichotomizing pre-diagnostic serum protein concentration according to the median of the control population, we found that both high levels of EGFR and ErbB2 were associated with glioblastoma risk." (PMID 26906551, 2016). "Previous SNP analysis of glioma patients indicated ERBB2 as a low penetrance gene associated with risk of glioblastoma development." (PMID 25537509, 2015). "Using our “Mutagrator tool”, we determined that an analogous mutation has been reported in a glioblastoma in ERBB2 (Glu914Lys)." (PMID 17487277, 2007). "This mutation is analogous to the previously reported Glu914Lys kinase domain mutation in ERBB2 found in a glioblastoma." (PMID 17487277, 2007). "CAR-T cell therapies targeting IL-13Rα2, EGFRvIII and HER2 (ErbB2) have been explored in patients suffering from recurrent glioblastoma and resulted in acceptable safety with some signs of clinical activity." (PMID 40102596, 2025). "The tumor-targeting domains of the bispecific antibodies were also functional, indicated by a strong binding of NKAB-EGFR and less pronounced binding of NKAB-ErbB2 to T98G glioblastoma cells, which express high levels of EGFR and more moderate levels of ErbB2." (PMID 38334638, 2024). "ErbB2 expression was assessed in 56 primary human glioblastoma tissue samples, revealing its potential as a therapeutic focus." (PMID 38694508, 2024). "In addition, higher mRNA levels of EGFR and ERBB2 were linked to increased immune infiltration in glioblastoma, suggesting their potential as therapeutic targets and prognostic markers in GBM." (PMID 39139341, 2024). "Intralesional therapy with third party, off-the-shelf NK-92/5.28.z cells is currently being explored in a phase I clinical trial (NCT03383978) in patients with recurrent ErbB2-positive glioblastoma." (PMID 37662907, 2023). "In glioblastoma, EGFR variant III, ERBB2/HER2, and IL-13 receptor α2 (IL13Rα2) are important CAR-T cell therapy targets that have been investigated in many clinical trial studies." (PMID 37420216, 2023). "Elimination of glioblastoma by NK cells, was markedly enhanced through expression of chimeric antigen receptor (CARs), targeting relevant antigens such as ErbB2 (HER2)." (PMID 36792722, 2023). "In Bredel’s dataset, the expression of ERBB2 was 3.065 times higher in glioblastoma tissues than in normal tissues." (PMID 33892666, 2021). "It was reported that CD151-α3β1 integrin complex can interact with EGFR to promote tumor invasion of glioblastoma, and integrin-associated CD151 can promote progression and metastasis of tumor mediated by ErbB2." (PMID 34108040, 2021). "CAR T cells were shown to inhibit GL261/EGFRvIII tumor growth, and the potential of ErbB2-specific CAR-NK (NK-92/5.28) cells was demonstrated for adoptive immunotherapy of glioblastoma." (PMID 33572835, 2021). "For example, an ErbB2 (HER2)-specific CAR-NK is currently being used in a phase I clinical trial for treatment of glioblastoma patients." (PMID 33995422, 2021). "We then outline preclinical approaches that employ CAR-NK cells for GB immunotherapy, and give an overview on the ongoing clinical development of ErbB2 (HER2)-specific CAR-NK cells currently applied in a phase I clinical trial in glioblastoma patients." (PMID 31798595, 2019).
glioblastoma (continued). "Because of these promising preclinical data, the ErbB2-specific NK-92/5.28.z CAR-NK cells were chosen for further development toward clinical application in glioblastoma patients (described in the following sections)." (PMID 31798595, 2019). "In a subsequent phase I dose-escalation trial at Baylor College of Medicine, the same group treated 17 patients with progressive ErbB2-positive glioblastoma by systemic infusion of one or more doses of up to 108/m2 autologous ErbB2-specific CAR-T cells." (PMID 31798595, 2019). "ErbB2/HER2-specific CAR-NK-92 cells showed very encouraging efficiency in target therapy of glioblastoma in an animal model." (PMID 30255103, 2018). "In this model, the majority of mice carrying syngeneic intracranial GL261/ErbB2 glioblastomas were cured upon repeated intratumoral injection of ErbB2-specific NK-92/5.28.z cells, while unmodified parental NK-92 cells were unable to inhibit tumor progression." (PMID 28572802, 2017). "This includes tumor cells exhibiting only moderately enhanced expression of the chosen target antigen, as demonstrated for established and tumor-initiating primary glioblastoma cells exposed to ErbB2-specific NK-92/5.28.z cells." (PMID 28572802, 2017). "In the present study, we investigated the possibility of using peptide immunotherapy for glioblastoma by using ERBB2-, BIRC5- and CD99-specific CTLs generated by multipeptide-pulsed DCs." (PMID 27409668, 2016). "In summary, we have described a branched multipeptide vaccine capable of stimulating a response to multiple CD8+ T cell epitopes from glioblastoma-TAAs such as ERBB2, BIRC5 and CD99." (PMID 27409668, 2016). "Our data provide first evidence that increased serum EGFR and ErbB2 levels can be detected in glioblastoma patients more than a decade before diagnosis, indicating that both proteins are important early in gliomagenesis." (PMID 26906551, 2016). "In the present study, we designed a peptide immunotherapy for glioblastoma using ERBB2, BIRC5 and CD99 peptides as TAAs." (PMID 27409668, 2016). "The human c-ErbB2 gene (HER2) is an equivalent of the rat neu gene, detected in a series of rat neuro/glioblastomas." (PMID 24205004, 2013). "In the case of NK-92, treatment with a single dose of a CAR-engineered variant targeting ErbB2 (HER2) did not induce an immune response against the effector cells in our ongoing clinical trial in glioblastoma patients." (PMID 37686586, 2023). "Currently, the NK-92/5.28.z cell line is being tested in a phase I clinical trial for the treatment of recurrent ERBB2-positive glioblastoma, and the results could aid in extending this approach to other disease entities." (PMID 33809981, 2021). "The trained KPNN models recapitulated characteristic molecular differences between glioblastoma cell states, including an association of HIF1A regulatory importance with MES cells and of ERBB2 with NPC cells." (PMID 32746932, 2020). "In a 3 + 3 dose escalation Phase I clinical trial (CAR2BRAIN; NCT0338978), patients with recurrent HER2-positive glioblastoma, with an already scheduled relapse resection surgery, received 1 × 107, 3 × 107 or 1 × 108 ErbB2-NK-92/5.28z CAR-NK cells/2ml injected intracranially." (PMID 32751977, 2020). "Although the mechanisms underlying the regulation of ErbB2 expression by DSE require further investigation, our inhibitor experiments suggest that EGFR/ErbB2 signaling could involve in the development of DSE-mediated malignant phenotypes in glioblastoma cells." (PMID 29864158, 2018). "Our data show that DSE regulates EGFR/ErbB2 signaling, and DSE expression may be positively associated with ErbB2 levels in glioblastoma cells." (PMID 29864158, 2018). "CAR-T cells could overcome trastuzumab resistance and target tumours that express ERBB2 at moderate levels (e.g., osteosarcoma, glioblastoma, and medulloblastoma) that commonly escape trastuzumab treatment." (PMID 28885562, 2017).
glioblastoma (continued). "In our study, the long lag time (almost 15 years) between sample donation and glioblastoma diagnosis indicates that increased serum EGFR and ErbB2 are likely to be associated with an etiological factor more than with the effects of undiagnosed disease (i.e., reverse causation)." (PMID 26906551, 2016). "Ligand-mediated chronic activation of EGFR is necessary for gliomagenesis in mice, and this association might be consistent with our finding of time-stable, elevated serum EGFR and ErbB2 levels in glioblastomas." (PMID 26906551, 2016). "HER2/ErbB2 overexpression drives gliomagenesis through ErbB2 heterodimerization-induced tyrosine autophosphorylation and constitutive activation of proliferative signaling pathways, ultimately promoting uncontrolled cellular proliferation and malignant transformation in glioblastoma." (PMID 40386781, 2025). "We found that EGFR and ERBB2 mRNA expression levels were higher in glioblastoma (GBM, WHO IV) than in other grades (WHO grade II & III), while the ERBB3 and ERBB4 mRNA expression levels were the opposite." (PMID 33892666, 2021). "Furthermore, in an immunocompetent GB mouse model, NK-92/5.28.z cells displayed strong immunomodulatory activity and enhanced endogenous antitumor immunity upon intratumoral injection, resulting in tumor rejection in the majority of mice carrying syngeneic intracranial GL261/ErbB2 glioblastomas." (PMID 31798595, 2019). "NK-92 cells expressing receptor tyrosine kinase ErbB2 (HER2)-specific CAR were also shown to regress glioblastoma (GBM) tumors in an orthotopic GBM xenograft model." (PMID 28955340, 2017). "The research revolves around the examination of a clonal product, ErbB2‐CAR‐NK‐92, intended for patients with glioblastoma." (PMID 40060757, 2025). "Applied individually, in in vitro cell-killing assays, these NKAB-EGFR and NKAB-ErbB2 antibodies specifically redirected NKAR-NK-92 and NKAR_RD-IL15-NK-92 cells to glioblastoma and other cancer cells with elevated EGFR or ErbB2 levels." (PMID 38334638, 2024). "Promising results have been demonstrated with ErbB2/HER2-specific NK cells in preclinical models of GBM, where they were shown to selectively target and kill glioblastoma cells both in vivo and in vitro." (PMID 38264122, 2023). "Oncogenes including EGFR, PDGFRA, ERBB2, and Proto-Oncogene tyrosine-protein kinase (KIT) are found on ecDNA in glioblastoma and are amplified in huge numbers that have a key role in cancer promotion, according to research." (PMID 35614494, 2022). "Top hub nodes from glioblastoma multiforme networks contain six matches, namely cyclin dependent kinase 2 (CDK2), cyclin A2 (CCNA2), cyclin B1 (CCNB1), erb-b2 receptor tyrosine kinase 2 (HER2), cyclin E1 (CCNE1), and cyclin D3 (CCND3)." (PMID 31952211, 2020). "The therapeutic utility of CAR-engineered NK cells for the treatment of glioblastoma has so far mainly been investigated in preclinical studies with effector cells targeting EGFRvIII, EGFR or ErbB2." (PMID 31798595, 2019). "Pre-clinical studies of CAR NK-92 targeting receptor tyrosine-protein kinase erbB-2 (ErbB2)/HER2 and EGFR showed promising results in glioblastoma and renal carcinoma lung metastases, respectively." (PMID 31540435, 2019). "HB-EGF mRNA expression is two- to five-fold higher in human glioblastomas than in normal brain tissue, and the HB-EGF receptors—EGFR homodimer and EGFR/ErbB2 heterodimer—are both commonly amplified in glioblastomas." (PMID 29864158, 2018). "This has been investigated with NK-92 cells-expressing second-generation CARs targeting ErbB2, EGFR, or mutant EGFRvIII, which are expressed by a large proportion of human glioblastomas." (PMID 28572802, 2017). "First, the cytotoxic activity of NKAR-NK-92 and NKAR_RD-IL15-NK-92 cells against homogeneous cultures of GL261/EGFR, GL261/ErbB2, and GL261/ErbB2/EGFR glioblastoma cells in the presence of NKAB-EGFR or NKAB-ErbB2, or a combination of both molecules, was tested." (PMID 38334638, 2024).
glioblastoma (continued). "However, in mixed glioblastoma cell cultures, used as a model for heterogeneous target antigen expression, NKAR-NK cells only lysed the EGFR- or ErbB2-expressing subpopulations in the presence of one of the NKAB molecules." (PMID 38334638, 2024). "Given this, we sought to uncover and characterise the PRM interactome of the RTKs epidermal growth factor receptor (EGFR), FGFR2 and ERBB2/HER2 in cell lines resembling oesophageal adenocarcinoma (OAC), breast adenocarcinoma (BrAC), glioblastoma (GBM) and lung squamous cell carcinoma (LSCC)." (PMID 39165974, 2024). "RTK signaling is the most commonly altered pathway in glioblastomas, with genetic alterations occurring in 86% of tumors, including epidermal growth factor receptor (EGFR), erb-B2 receptor tyrosine kinase 2 (ERBB2), and platelet-derived growth factor receptor (PDGFR)." (PMID 36795488, 2023). "Branched multipeptides from ERBB2, BIRC5, and CD99 stably bound with T2 cells, and multipeptide-pulsed denditric cells–cytotoxic T lymphocytes exhibited remarkable cytotoxic activity against primary glioblastoma cells." (PMID 29534016, 2018). "This alanine residue is perfectly conserved within the Furin-like domain among other epidermal growth factor genes and appears mutated also in ERBB2 and ERBB4, although not in glioblastoma." (PMID 26860319, 2016). "The poor efficacy of single treatments may be explained by concurrent activation of multiple RTKs in glioblastoma, including EGFR, ERBB2, PDGFRA and MET." (PMID 23874926, 2013). "Moreover, HER2-targeted CAR-NK cells and ErbB2-targeted CAR-NK cells might be feasible and safe in recurrent glioblastoma." (PMID 39555054, 2024). "In the present study, canine osteosarcoma, human osteosarcoma and glioblastoma cell lines, exhibited similar response to single CT treatment and cancer cell death was further enhanced by introducing another STAT3/5 inhibitor, a proteasome inhibitor drug, and an EGFR/ErbB2 inhibitor." (PMID 33544704, 2021). "Therefore, targeting ERBB receptor family members like EGFR, ERBB2 or ERBB3 alone or in combination with other epithelial markers such as EpCAM, will provide opportunities to detect and isolate CTCs that represent primary tumors of ovarian and glioblastoma." (PMID 29321816, 2017). "We further confirmed the cytotoxic potential of our lead combination involving EGFR/ERBB2 inhibitor (lapatinib) with DDR1/BCR-ABL inhibitor (nilotinib) in radioresistant spheroids of HCT116 (COAD) and, in an additional devastating primary cancer model, glioblastoma (GBM)." (PMID 35664781, 2022). "In our previous study, we detected positive expression of v-erb-b2 erythroblastic leukemia viral oncogene homolog-2 (ERBB2), baculoviral IAP repeat containing-5 (BIRC5) and the glycoprotein CD99 in most glioblastoma tissues, and negative expression in normal brain tissues." (PMID 27409668, 2016). "Sera from these mice contained IgG antibodies reactive with both GL261/ErbB2 and ErbB2-negative, but otherwise isogenic GL261 cells, indicating that the induced protective antitumor immune response was broadly directed against the glioblastoma cells and not limited to the CAR target antigen." (PMID 28572802, 2017).